SLC38A1 (solute carrier family 38 member 1)
Diseases named in the same sentence as SLC38A1 in open-access papers (continued):
Sharing a sentence is not in itself a finding about the gene and the disease.
endometrial cancer (3 papers, 2017 to 2025). Primary or metastatic malignant neoplasm involving the endometrium (mucous membrane that lines the endometrial cavity). "It has been previously reported that SLC38A1 may serve an important role in lung, breast, liver, colorectal, and endometrial cancers." (PMID 40075587, 2025). "For endometrial cancer, ectopically expressed CENP-A upregulates SLC38A1 (Solute Carrier Family 38 member 1), leading to the enhancement in metabolism reprogramming and glutamine uptake, which subsequently contribute to its aggressiveness and poor prognosis." (PMID 39273649, 2024).
liver cancer (3 papers, 2014 to 2022). An epithelial or non-epithelial malignant neoplasm that arises from the liver. "High levels of hepatic SLC38A1 in patients with liver cancer cause lower OS and RFS." (PMID 35663198, 2022). "However, the relationship between SLC38A1 and prognosis and/or recurrence of liver cancer is yet unreported." (PMID 35663198, 2022). "In addition, there are no reported investigations on the association between SLC38A1 and the prognosis of liver cancer patients with ASH." (PMID 35663198, 2022). "Based on our analysis, miRNA-432 targeted SLC38A1, and the levels of miRNA-432 and SLC38A1 could accurately predict the overall survival (OS) and relapse free survival (RFS) in patients with liver cancer." (PMID 35663198, 2022).
sarcopenia (3 papers, 2024 to 2025). Progressive decline in muscle mass due to aging which results in decreased functional capacity of muscles. "Our study suggests the correlations of CLIC5 and SLC38A1 with AP and sarcopenia; nevertheless, we cannot deny that there are several limitations." (PMID 40785039, 2025). "In both test datasets (GSE149331 and GSE8479), the expression of CLIC5 and SLC38A1 was significantly downregulated in AP and sarcopenia, while the expression of C1QB was significantly upregulated." (PMID 40785039, 2025). "This study revealed for the first time that CLIC5 and SLC38A1 were shared biomarkers for AP and sarcopenia." (PMID 40785039, 2025). "In conclusion, our study showed CLIC5 and SLC38A1 as shared genes of AP and sarcopenia in immune dysregulation and metabolic stress." (PMID 40785039, 2025). "Among them, MYH8, HOXB2, C1QA, CDKN1A, and SLC38A1 are associated with sarcopenia, and in this study, LGR5, SERPINA5, and TPPP3 genes were found to be associated with Sarcopenia for the first time." (PMID 38229116, 2024). "The diagnostic value of CLIC5, SLC38A1 and C1QB was performed by receiver operating characteristic curves and the area under the curve in the datasets, and the validation results confirmed a consistent trend of downregulation of CLIC5 and SLC38A1 in AP and sarcopenia." (PMID 40785039, 2025). "In sarcopenia, the downregulation of SLC38A1 leads to inadequate amino acid supply to muscle cells, inhibiting protein synthesis and causing metabolic disorders, which may exacerbate pancreatic cell damage and inflammation after the onset of acute pancreatitis." (PMID 40785039, 2025). "In patients with sarcopenia, the expression of TPPP3, C1QA, LGR5, MYH8, and CDKN1A genes are upregulated, and the expression of SLC38A1, SERPINA5, and HOXB2 genes are downregulated." (PMID 38229116, 2024).
gout (2 papers, 2020 to 2023). A condition characterized by painful swelling of the joints, which is caused by deposition of urate crystals. "Because genetic variants in urate transporter genes such as ABCG2, SLC2A9 and SLC22A12 are well known to cause SUA variation and gout, it is also possible that the SLC38A1/SNAT1 transporter is involved in urate or purine transport." (PMID 32238385, 2020).
hepatoblastoma (2 papers, 2017 to 2019). Hepatoblastoma (HB) is a malignant hepatic tumor and is the most common pediatric liver cancer. "The interaction between β-catenin and YAP-1 protein may activate mTOR pathway to increase the expression of amino acid transporter, i.e. SLC38A1, which may be critical in the development of hepatoblastoma." (PMID 31511432, 2019). "Silencing of YAP led to decrease in the SLC38A1 expression and inhibition of mTORC1 suggesting that the activation of YAP-β catenin may induce activation of mTORC1 to promote the development of hepatoblastoma by inducing the expression of SLC38A1." (PMID 31511432, 2019).
metastatic melanoma (2 papers, 2022). A melanoma that has spread from its primary site to another anatomic site. "Furthermore, although high expression of most amino acid transporters was correlated with increased mortality, elevated expression of SLC38A1 (glutamine transporter) and SLC7A7 (lysine transporter) had strong benefits for patients with metastatic melanoma." (PMID 36457136, 2022).
alcoholic hepatitis (1 paper, 2023). Acute hepatitis resulting from ingestion of alcohol. "Furthermore, miR-214, which is upregulated in alcoholic hepatitis, increases ferroptosis by activating ferroptosis-driver genes (ACSL4, PRKAA2, and SLC38A1) through AGO2-dependent transcriptional mechanisms." (PMID 37626043, 2023).
behavioral disorders (1 paper, 2019). "Here we found that SNAT1 was predominantly expressed in cerebral neurons, and Slc38a1 deficiency did not conferred any behavioral disorders but resistance to ischemic brain damage." (PMID 31552299, 2019).
COVID-19 (1 paper, 2021). A disease caused by infection with severe acute respiratory syndrome coronavirus 2. "Marker genes attributed to the “mild mature activated” neutrophil subset, such as ITGA4 or SLC38A1, were indeed elevated as well in the mild COVID-19 patients’ granulocytes of this study." (PMID 33441124, 2021).
Insulin resistance (1 paper, 2019). Increased resistance towards insulin, that is, diminished effectiveness of insulin in reducing blood glucose levels. "Ectonucleotide pyrophosphatase/phosphodiesterase 5 (ENPP5), SLC38A1, and TM4SF1 are novel biomarkers for the development of insulin resistance." (PMID 30678306, 2019).
intrauterine growth restriction (1 paper, 2024). "In research on the pathogenesis of selective intrauterine growth restriction (sIUGR), overexpression of hypoxia-inducible factor (HIF-1α) induces upregulation of SLC38A1, which reduces cell growth and migration." (PMID 39834787, 2024).
keloid (1 paper, 2024). An irregularly shaped, elevated mark on the skin caused by deposits of excessive amounts of collagen during wound healing. "In summary, we identified AKR1C3, PLIN2, SOCS2, SLC38A1, and SNCA as characteristic genes associated with ferroptosis in keloids through comprehensive transcriptomic data analysis." (PMID 39834787, 2024). "Our research finds that SLC38A1 is downregulated in keloids, suggesting that it may have a significant impact on processes such as inflammation and cell proliferation." (PMID 39834787, 2024). "As shown in, at the protein level, the expression of PLIN2 and AKR1C3 was significantly increased in keloid samples compared to normal samples, whereas the expression of SOCS2, SLC38A1, and SNCA was significantly decreased." (PMID 39834787, 2024). "Additionally, as depicted in, at the mRNA level, there was also a significant increase in the expression of PLIN2 and AKR1C3 in keloid samples, and a significant decrease in the expression of SOCS2, SLC38A1, and SNCA." (PMID 39834787, 2024).
liver fibrosis (1 paper, 2025). "Currently, research on SLC38A1 in liver fibrosis is limited, but it is associated with non-alcoholic fatty liver disease fibrosis." (PMID 40943308, 2025). "Interestingly, we also found that Slc38a1 expression was upregulated in BDL-induced mouse liver fibrosis, suggesting that SLC38A1 may be a key diagnostic and therapeutic gene for cholestatic liver fibrosis." (PMID 40943308, 2025). "Our research also indicates that SLC38A1 expression is upregulated in human liver fibrosis groups." (PMID 40943308, 2025).
non-small cell lung carcinoma (1 paper, 2024). A group of at least three distinct histological types of lung cancer, including non-small cell squamous cell carcinoma, adenocarcinoma, and large cell carcinoma. "In contrast, it showed that SLC1A4 expression is downregulated in non-small cell lung cancer cells (NSCLC), while SLC38A1, SLC1A5, SLC7A5, and SLC7A11 were upregulated." (PMID 38705513, 2024).
oral carcinomas (1 paper, 2024). "The significant upregulation of SLC38A1 mRNA levels in oral carcinomas as compared to normal control specimens prompted us to investigate the possible amplification of the SLC38A1 gene in OTSCC species." (PMID 38254895, 2024). "External transcriptomic datasets and Western blot analyses showed upregulation of SLC38A1 mRNA/protein in human OTSCC and oral cancer cell lines as compared to the corresponding controls." (PMID 38254895, 2024).
osteoarthritis (1 paper, 2025). A noninflammatory degenerative joint disease occurring chiefly in older persons, characterized by degeneration of the articular cartilage, hypertrophy of bone at the margins and changes in the synovial membrane. "Quercetin alleviates the progression of osteoarthritis by regulating inflammatory cascades and chondrocyte apoptosis, and SLC38A1 may serve as an intermediate through which it exerts these effects." (PMID 40809843, 2025). "Although there are currently no reports on the functional mechanism of the SLC38A1 gene in osteoarthritis, many other members of the solute carrier family have been reported to play a role in OA." (PMID 40809843, 2025). "Moreover, the correlation analysis of SLC38A1 and STX11 with all immune cells showed a negative correlation with NK cells, further suggesting that SLC38A1 and STX11 may influence the development of osteoarthritis through the immune infiltration of NK cells." (PMID 40809843, 2025).
preeclampsia (1 paper, 2022). Preeclampsia is a hypertensive disorder of pregnancy that is characterized by new-onset hypertension with proteinuria presenting after 20 weeks of gestation, and depending on mild or severe forms may initially present with severe headache, visual disturbances, and hyperreflexia. "We next assessed gene and protein expressions of SLC38A1, SLC38A2, and SLC38A4 in IUGR alone or in preeclampsia + IUGR placental samples collected from late preterm (34–36 weeks) gestation and compared these to gestationally matched controls." (PMID 36613847, 2022). "We assessed gene and protein expressions of SLC38A1, SLC38A2, and SLC38A4 in IUGR alone or preeclampsia + IUGR placental samples collected from early preterm (<34 weeks) gestation and compared these to gestationally matched uncomplicated preterm controls." (PMID 36613847, 2022).
steatosis (1 paper, 2022). Increased lipid within the cytoplasm of cells. "The SLC38A1 protein displayed an elevated expression in HCC tissues with steatosis." (PMID 35663198, 2022).
Yoon-Bellen neurodevelopmental syndrome (1 paper, 2023). "In proband BR1, the heterozygous deletion did not contain dominant disease genes, but three recessive genes (SLC38A1, CHAT and OGDHL) with a muscle phenotype: congenital myasthenic syndrome type 21 or type 6, or Yoon-Bellen neurodevelopmental syndrome, respectively." (PMID 36781956, 2023).
cancer (47 papers, 2013 to 2025). A tumor composed of atypical neoplastic, often pleomorphic cells that invade other tissues. "Among these, SLC1A5 (also known as ASCT2), SLC7A5 (LAT1) and its heavy chain SLC3A2 (CD98hc), and SLC38A1 (SNAT1) are highly expressed in various cancers and have been implicated in tumor progression, therapeutic resistance and clinical outcome." (PMID 40707944, 2025). "Similarly, SLC38A1 is upregulated in various cancer types and has been implicated in supporting cell survival and proliferation when GLN availability is limited." (PMID 40711148, 2025). "SLC38A1 expression in cancer tissue was associated with poorer prognosis." (PMID 24712400, 2014). "Among AATs, SLC38A1 plays a central role in glutamine transport, and its overexpression is frequently observed in cancers, including breast, lung, colon, and endometrial malignancies." (PMID 40723891, 2025). "Other transporters involved in glutamine metabolism, SLC38A1 and SLC38A5, have been implicated in the uptake of glutamine, which is essential for cancer cell metabolism and growth." (PMID 40362545, 2025). "SLC38A1 (Solute Carrier Family 38 Member 1) is an amino acid transporter that plays a significant role in cancer metabolism." (PMID 40315269, 2025). "By function assay, we found that circTADA2A exhibit its inhibitory effects in cancer progression via interacting with CNBP proteins to regulate SLC38A1 transcription." (PMID 38635778, 2024). "The expression of SLC38 family members including SLC38A1-11 in GC patients was analyzed in The Cancer Genome Atlas (TCGA) data using the Gene Expression Profiling Interactive Analysis (GEPIA) platform." (PMID 39357829, 2024). "Previous studies have reported the upregulation of SLC38A2 in cancer cells with knock-down of the SLC38A1 gene, indicating a possible compensatory functional overlap between SLC38 protein members." (PMID 38254895, 2024). "The sodium-coupled neutral amino acid transporter 1 (SLC38A1), an important amino acid transporter for energy metabolism and cell physiology, has key roles in neurotransmission, embryonic development, and cancer." (PMID 35837487, 2022). "Studies have shown that SLC38A1 is overexpressed in malignant tumors and can promote the proliferative, invasive, and metastatic potentials of tumor cells." (PMID 34697542, 2021). "The results showed that ALOX12, ANGPTL7, DRD4, and MAPK9 remarkably decreased within ESCC samples relative to non-carcinoma samples, whereas SLC38A1 and ZNF419 were highly expressed." (PMID 34291083, 2021). "The median survival was 46.69 months in patients with SLC38A1-positive cancers, and 69.7 months in subjects with SLC38A1-negative cancers (P = 0.002)." (PMID 24712400, 2014). "Strong staining of SLC38A1 protein in the cytoplasm was found in 495 out of the 896 cancer samples in both the well differentiated, and poorly differentiated cancer cells." (PMID 24712400, 2014). "Indeed, SLC38A1 and 2 have been described as neutral amino acid “loaders” in cancer cells, thus allowing rapid and direct influx of specific amino acids, such as glutamine." (PMID 39062801, 2024). "SLC38A1 mRNA was indeed upregulated in the carcinomas compared to normal controls." (PMID 38254895, 2024). "As the malignant oral epithelial cells CaLH3 and SCC25 showed robust expression of SLC38A1 as compared to the normal oral keratinocytes, we hypothesized that SLC38A1 was upregulated in carcinomas as compared to the corresponding control specimens." (PMID 38254895, 2024). "Indeed, SLC38A1 has confirmed roles in mouse placental development and cancer cell growth and migration." (PMID 35837487, 2022). "Similarly, we predict that inhibiting the glutamine transporter Slc38a1/2 in cancer will result in cancer stem cells exiting the quiescent CSC stage." (PMID 36230891, 2022).
cancer (continued). "Recently, SNAT1/2 (SLC38A1/2) have been implicated as important players in maintenance of cellular glutamine levels in the absence of ASCT2, thus broadening the role of glutamine transport in cancer cells and mTORC1 activity." (PMID 29326164, 2018). "However, although SLC1A5 is the major glutamine transporter, with high affinity and high capacity observed in many cancer types, other members of the solute carrier superfamily including SLC7A5 (LAT1) and SLC38A1/2 (SNAT1/2) have also been linked to tumor-specific glutamine uptake." (PMID 38641063, 2024). "Actually, other SLCs, such as SLC38A1 and SLC12A8, are also involved in cancer development and drug resistance by regulating the AKT signaling." (PMID 39949345, 2025). "SLC38A1 was upregulated in OSCC, suggesting a role in the uptake of glutamine, which is essential for cancer cell metabolism and proliferation." (PMID 40362545, 2025). "Similar to cancer cells, activated T cells upregulate glutamine transporters (including SLC1A5/ASCT2 and SLC38A1/SNAT1) and increase glutaminolysis to accommodate the demands of rapid proliferation." (PMID 39211039, 2024). "Thus, SLC38A1 may be upregulated in cancer cells requiring consistently high levels of glutamine." (PMID 38254895, 2024). "Among them, ASCT2 (SLC1A5), SNAT1 (SLC38A1) and SNAT2 (SLC38A2) play a major role in cancer cells, since ASCT2 is required for optimal growth at low glutamine concentrations, whereas SNAT1 and SNAT2 mainly mediate net glutamine uptake for glutaminolysis." (PMID 36768660, 2023). "Here are just a few examples: SNAT1 (SLC38A1), SNAT2 (SLC38A2), and ASCT2 (SLC1A5) are the major Gln transporters in cancer cells." (PMID 33477430, 2021). "The transporters capable of importing glutamine such as ATB0,+ (SLC6A14 gene), SNAT1 (SLC38A1 gene), ASCT2 (SLC1A5 gene), LAT1 (SLC7A5 gene), and LAT2 (SLC7A8 gene) are crucial in cancer metabolic remodeling often being upregulated in tumors." (PMID 32993063, 2020). "Unlike what we observed in murine HCC, SLC38A1 was globally expressed in all human cancer cells, alongside SLC38A2 being the most highly expressed glutamine transporter in all studied HCC cells." (PMID 39062801, 2024). "SLC1A5 and SLC38A1 cotransport polarized Na+ and glutamine, and SLC1A5 has been identified as amino acid harmonizer, whereas SLC38A1 has been recognized as an amino acid loader in cancer cells." (PMID 36262284, 2022). "Furthermore, it has been demonstrated that SLC38A1/SNAT1 and SLC38A2/SNAT2 activity is essential to mediate net glutamine uptake and glutaminolysis in cancer cells, whereas SLC1A5/ASCT2 and SLC7A5/LAT1 coordinate intracellular amino acid pools." (PMID 34003553, 2021). "The import of 90% of the net amino acid demand is mediated directly or indirectly by SNAT1 (SLC38A1) and SNAT2 (SLC38A2), because they are the main neutral amino acid loaders in cancer cells and provide exchange substrates for antiporters to capture amino acids not transported by SNAT1 and SNAT2." (PMID 32859034, 2020).